TNF (tumor necrosis factor)
Diseases named in the same sentence as TNF in open-access papers (continued):
Sharing a sentence is not in itself a finding about the gene and the disease.
COVID-19 (continued). "Interestingly, the secretion of IL-6, IL-8, TNF-α, IFN-γ and IL-10 was significantly elevated in CARγ and CARζ cells treated with SARS-CoV-2 virions, suggesting that these CAR macrophages may not be suitable for application in severe patients or patients with late-stage COVID-19." (PMID 34367135, 2021). "A previous study revealed that intensive care unit (ICU) patients with COVID-19, including ARDS, had an abundance of proinflammatory cytokines, including IL-2, IL-7, IL-10, GCSF, IP10, MCP1, MIp1A, and TNFα, compared to non-ICU patients." (PMID 34161373, 2021). "Significantly elevated levels of the inflammatory cytokines TNF-α, IL-1, IL-6, IFN-λ3, IL-6, IP-10, and CXCL9 have been documented in severe COVID-19 compared to non-severe disease cases." (PMID 34399775, 2021). "Proinflammatory molecules, such as IL-2, IL-4, IL-5, IL-6, IL-10, IL-13, TNF-α, IFN-Υ, and CRP, were found at higher levels in COVID-19 patients with DM than in COVID-19 patients without DM." (PMID 34786431, 2021). "In the nonsevere COVID-19 group, the correlation coefficients of IL-4 and IL-2, TNF-α and IL-2, TNF-α and IFN-γ, and TNF-α and IL-4 were 0.887, 0.795, 0.699, and 0.674, respectively." (PMID 34712741, 2021). "In the COVID-19 study, it was notable that the increased frequencies of DNBC were observed in the absence of GC, reduced GCBC and elevated TNF-α." (PMID 34938286, 2021). "TNF-α, IFN-γ, and IL-2 were also higher while IL-4 was lower in severe COVID-19 cases than in mild cases, but the difference was not significant." (PMID 32669467, 2020). "In the registered IBD patients with COVID-19 from SECURE-IBD, there were 762 patients with anti-TNFα therapy alone, 651 (85%) of whom recovered without hospital admission and four patients died in total." (PMID 33511147, 2020). "COVID-19 nonsurvivors had quantitatively low ELISpot IFN-ɣ and TNF-α production, although the difference was not statistically significant (red dots)." (PMID 32687484, 2020). "In contrast, tumor necrosis factor (TNF)-α expression was higher in the lungs, intestine, liver, and kidneys, but not in the spleen, of all COVID-19 patients (compared to levels in controls)." (PMID 33424804, 2020). "In classical monocytes from patients with severe COVID-19, type I IFN response co-existed with the TNF/IL-1β-driven inflammation, and this was not seen in patients with milder COVID-19." (PMID 32651212, 2020). "CD73- cells were generally more capable of secreting GrB, perforin, TNF-α, or IFN-γ regardless of the disease status, but this effect was stronger in lymphocytes obtained from COVID-19 patients compared to those obtained from healthy donors." (PMID 32707842, 2020). "In a study of 46 patients with COVID-19-related ARDS, the levels of IL-6, IL-8, and TNF-α were lower compared with 51 SARS-CoV-2 negative patients with ARDS as a result of septic shock." (PMID 33505321, 2020). "At moderate exposure level, the COVID-19-positive individual exhibited higher cytokine peaks following the heterologous booster, whereas the COVID-19-negative individuals showed attenuated responses for IFN-γ, TNF, and IL-10." (PMID 40406109, 2025). "Patients with ILD showed no significant elevation in cytokines (IL-6, TNF-α, and IFN-γ), inflammatory biomarkers, C-reactive protein, ferritin, or D-dimer, indicating that patients with COVID-19 and ILD did not manifest additional hyperinflammation compared with the control individuals." (PMID 40573986, 2025). "No threshold for serum TNF-α levels in MIS-C was found in the literature; however, several studies claimed that TNF-α discriminated between patients with MIS-C and severe COVID-19 or differentiated MIS-C children with cardiac manifestations from those without cardiac manifestations." (PMID 39685637, 2024).
COVID-19 (continued). "We found that the patients who had severe COVID-19 had low or absent cellular immune responses of CD4+IL-2+, CD4+IFN-γ+IL-2+, CD8+IFN-γ+IL-2+, and CD8+IFN-γ+IL-2+TNF-α+ after a booster dose, in line with the relevance of polyfunctional T cell responses against viruses." (PMID 37243116, 2023). "The levels of Eotaxin, Eotaxin-3 and IL-10 were exclusively elevated in severe SOT COVID-19 whereas IL-16, IL-1RA, IL-1α, MIP-1α and TNF-α, were solely increased in Non-SOT COVID-19 patients with severe disease, as compared to their respective mild/moderate group." (PMID 35075453, 2022). "Interestingly, TNFα, IL-27, IL-17A and IL-12 plasma levels of SARS-CoV-2 negative HD patients were in a similar range as in moderate and severe COVID-19 non-HD patients." (PMID 35265078, 2022). "Also, those COVID-19 patients in hospitalization had higher CCL2, CXCL10, and TNF-α than those who had a non-hospitalized and less severe condition." (PMID 35159388, 2022). "Both studies uniformly describe stable cellular immune responses against SARS-CoV-2 including IFN-γ release as does our study but also of other cytokines (IL-2, IL-4, TNF-α etc.)and proliferation assays in SOT convalescents similar to non-IS-Con up to twelve months after COVID-19." (PMID 36322587, 2022). "However, in COVID-19 multifunctional activated T cells secreting two of the three cytokines IFN-γ, IL-2, and TNF-α were reduced whilst T cells producing all three were non-functional." (PMID 33936053, 2021). "Additionally, in non-severe COVID-19—although significantly lower than severe ones—blood-cytokine levels (for example IL-1β, IL-1RA, IL-2R, IL-6, IL-7, IL-8, IL-9, IL-10, IFN-γ, TNF-α, G-CSF, GM-CSF, IP10, MCP1), can be increased." (PMID 34572585, 2021). "Whether GRO-a, IL-9, TNF-α and TNF-β play protective roles in COVID-19 has not been eliminated at present, which needs further confirmation by basic experiments." (PMID 34489933, 2021). "Since the lectin-like domain of TNF does not interfere with TNF’s anti-bacterial actions, while exerting protective actions in the alveolar-capillary compartments, it is currently evaluated in clinical trials in ARDS and COVID-19." (PMID 35264975, 2021). "A previous study found that intensive care unit (ICU) patients with COVID-19 had higher plasma levels of interleukin (IL)-10, IL-2, IL-7, tumor necrosis factor (TNF)-α, IP-10, monocyte chemoattractant protein 1, Macrophage inflammatory protein 1A than those in non-ICU patients with COVID-19." (PMID 32727465, 2020). "Furthermore, in contrast to the cells of COVID-19 patients, our cells exhibited several-fold lower IFN-γ production and no TNF induction." (PMID 33198287, 2020). "Similarly, in severe COVID-19 cases, ICU patients had higher plasma levels of IL-2, IL-7, IL-10, GSCF, MCP1, MIP1A, and TNFα compared to non-ICU patients." (PMID 32754890, 2020). "Interestingly, pro-inflammatory cytokines—such as IFN-gamma, TNF, IL-23, IL-15, IL-21 and IP-10/CXCL-10—were detected both in the sera of severe ICU hospitalized and of non-hospitalized COVID-19 patients." (PMID 33019628, 2020). "Serum inflammatory factor levels of IL-2, IL-1β, IL-5, IL-4, IL-6, IL-8, IL-10, IL-17, IL-12P70, IFN-α, TNF-α, IFN-γ, endotoxin, CRP, and hs-CRP of non-severe COVID-19 patients across different age groups (< 50, 50–60, 60–70, and ≥ 70 years) were not significantly different." (PMID 33065551, 2020). "Very recently, a cohort study showed that acute COVID-19 or postacute sequelae of COVID-19 (PASC) are not related to autoantibodies but to elevated plasma levels of proinflammatory cytokines such as interleukin-1 beta (IL-1β), IL-6, and tumor necrosis factor alpha (TNF-α)." (PMID 37095536, 2023).
COVID-19 (continued). "A persistent inflammatory state and immune activation, characterized by increased blood levels of the inflammatory cytokines–TNFα, IL-6, IL-1 and CRP, although not specific to COVID-19, may induce apoptosis with secondary endothelial dysfunction and may increase intrahepatic clot development risk." (PMID 36556915, 2022). "In fact, from the group comparison of COVID-19 vs. non-COVID-19, the authors identified 14 specific inflammatory proteins that can be related to SARS-CoV-2 infection, namely CXCL5, CXCL10, CXCL11, Gal-9, IL-18, IL-18R1, IFNγ, LIF-R, MCP-2, MCP-3, MERTK, MMP-1, PD-L1, and TNF." (PMID 35269564, 2022). "Serologic response to COVID-19 vaccines could be mounted in patients with IBD; however, its magnitude was significantly lower in patients treated with anti-tumor necrosis factor α (anti-TNF) agents regardless of administration timing and drug levels." (PMID 36366342, 2022). "On admission, there were higher serum concentrations of tumor necrosis factor α (TNFα) (p < 0.001), interleukin 1 β (IL-1β) (p < 0.001), pentraxin 3 (PTX3) (p < 0.001), resistin (p = 0.032), and lower concentrations of adiponectin (p < 0.001) between the severe COVID-19 and the non-severe patients." (PMID 36289725, 2022). "However, another study which included 25 confirmed COVID-19 patients who were admitted to ICU showed that circulating levels of IL-2, interleukin-4 (IL-4), tumor necrosis factor-α (TNF-α), interferon (IFN-γ) and CRP were not directly correlated with symptom severity of COVID-19." (PMID 34282057, 2021). "In addition, we could not demonstrate correlation between severity of COVID-19 and other established ARDS-related cytokines such as TNF-α, IL-1α, and IL-1β." (PMID 34938289, 2021). "Clinical evaluation of 41 COVID-19 patients (Non-ICU: 28 and ICU: 13) for over 26 chemokines and cytokines revealed increased levels of 16 of them such as IL-1β, IL-1RA, IL-17, IL-8, IL-9, IL-10, basic FGF, G-CSF, GM-CSF, IFN-γ, CXCL10, CCL2, CCL3, CCL4, PDGF, TNF-α." (PMID 33335518, 2020). "Another study that compared PCC patients with patients who had COVID-19 but did not present PCC, and patients who had PCC and recovered, showed that ongoing PCC could be characterised by higher circulating IL-1β, IL-6 and TNFα, 8 to 10 months after acute infection." (PMID 38549752, 2024). "Second, certain pro-inflammatory cytokines (IL2, IL7, IL10, GCSF, IP10, MCP1, MIP1A, and TNF) were further increased in ICU patients compared with non-ICU patients, indicating that excessive acute inflammatory responses may lead to septic shock and death in COVID-19 patients." (PMID 32442210, 2020).
colitis (2,603 papers, 1995 to 2026). Inflammation of the colon. "XXLP significantly improved colitis symptoms, including weight loss and colon shortening, and reduced the concentrations of inflammatory markers IL-1β, IL-18, TNF-α, and IL-6." (PMID 41901297, 2026). "Rag1−/− mice receiving CD4+ CD45Rbhi T cells alone developed severe colitis, as evidenced by increased weight loss, higher pathological scores, and intestinal TNF‐α and IL‐6 levels, which were inhibited by co‐transfer of WT or miR‐10a‐deficient Tregs." (PMID 41178490, 2026). "Mechanistically, Pum2 loss during colitis drives macrophage hyperactivation and TNFα-dependent epithelial necroptosis, which together intensify pathogenic macrophage-epithelial interactions and barrier breakdown." (PMID 41856997, 2026). "Nevertheless, many patients remain unresponsive to anti-TNF therapy and develop colitis-associated colorectal dysplasia or cancer, warranting restorative proctocolectomy." (PMID 40115777, 2025). "In this study, DSS-induced colitis in mice was associated with significant upregulation of IL-6, TNF-α, and IL-1β." (PMID 41257293, 2025). "In dextran sodium sulfate (DSS)-induced colitis, exogenous chemerin aggravated disease severity, causing greater weight loss, mucosal damage, and mortality, while elevating IL-6, TNF-α, and IFN-γ levels." (PMID 41301712, 2025). "Generally, the development of TNBS-induced colitis was associated with an increase in the local production of IL-12, TNFα, and IL-1β." (PMID 40305159, 2025). "It inhibits DSS-induced colitis, leading to reduced weight loss, inhibition of colonic pro-inflammatory cytokines such as TNF; and maintenance of intestinal transmembrane resistance." (PMID 40370467, 2025). "Inflammatory cytokines, such as TNF-α, IL-1β, and IL-6, are central mediators of the mucosal immune response and are closely linked to the pathogenesis of colitis-stimulated inflammation." (PMID 41614862, 2025). "TNF-α, which plays a causal role in the pathogenesis of colitis, acts as a central regulator in initiating and sustaining excessive inflammatory responses in the intestinal mucosa." (PMID 41515203, 2025). "Specifically, the plant’s ability to fight colitis was linked to higher IL-10, lower IL-6, and lower TNF-α levels." (PMID 40822453, 2025). "When tested in combination with anti-TNFα, this regimen significantly reduced body weight loss, ameliorated intestinal inflammation, and decreased leukocyte infiltration, overall improving colitis." (PMID 40642091, 2025). "This again caused anxiety behaviour with induced activation of IL-6, TNF-α and IL-1β expression, indicating colitis." (PMID 41462928, 2025). "This TNF-α/NF-κB-mediated inflammatory response is key to colitis development and strongly associated with colon cancer progression." (PMID 40607420, 2025). "AhR activation has been linked to the alleviation of colitis by reducing inflammatory cytokines like IL‐1β, IL‐6, and TNF‐α, while enhancing anti‐inflammatory cytokines, such as IL‐4, IL‐10, and IL‐22, and strengthening the intestinal epithelial barrier." (PMID 39836604, 2025). "All in all, improved colitis following anti-TNFα therapy in CD patients was associated with increased HDL-C levels." (PMID 40484317, 2025). "The development of colitis has been directly associated with inflammatory cytokines, such as IL‐6, IL‐17, TNF‐α, and interleukin 23 (IL‐23)." (PMID 39723032, 2024). "As colitis develops, intestinal lamina propria infiltrates immune cells, causing secretion of cytokines, particularly TNF-α, a pivotal mediator of inflammation and cell death and also a key therapeutic target in IBD treatment." (PMID 39688910, 2024). "To this end, we analyzed the main pro-inflammatory cytokines associated with DSS-induced colitis, such TNFα, IL-1β, IL-12p40, and IL-6, at the transcription level." (PMID 39456254, 2024).
colitis (continued). "The regional delivery of CNP-miR146a improved weight loss and decreased colon inflammation in mice in this model, as seen on histology and through the downregulation and normalization of proinflammatory cytokines IL-6 and TNF." (PMID 38786849, 2024). "Exposed IS caused colitis in mice, decreasing colon length and IL-10 levels and increasing myeloperoxidase, TNF-α, IL-1β, and IL-6 levels in the colon." (PMID 39519543, 2024). "Irrespective of the rBanLec treatment, induction of experimental colitis in both strains was associated with a simultaneous rise in local production of both TNFα and IL-10." (PMID 38892639, 2024). "Under similar conditions, orally injecting axenic Blastocystis ST7 into DSS-induced colitis mice exacerbated the severity of colitis by increasing the proportion of pathogenic bacteria and inducing pro-inflammatory IL-17A and TNF-α-producing CD4+ T cells." (PMID 38087868, 2024). "Pro-inflammatory cytokines such as IL-17, IL-1β, IL-6, and TNF-α have been identified as the key driver in colitis-associated inflammation." (PMID 39744127, 2024). "HT ameliorated DSS-induced colitis in mice, showing marked improvement in weight loss, colon length, colonic pathological severity, and the levels of TNFα and IL6 in serum." (PMID 39064786, 2024). "Another study has found that Cardamonin treatment attenuated intestinal disorders, including recurrent colitis and colitis-associated tumors, and reduced IL-1β and TNF-α secretion." (PMID 38473179, 2024). "Huangqin Decoction significantly alleviated colitis in mice, reducing body weight loss, disease activity, colon shortening, tissue damage, and levels of TNF-a, IL-6, IL-1β, and COX-2 induced by DSS treatment." (PMID 39411430, 2024). "TNF-α levels are one of the most used parameters to characterize experimental models of colitis-associated CRC26." (PMID 37729351, 2023). "TNF has long been implicated in the development of colitis, and indeed, the pharmacologic blockade of TNF with monoclonal antibodies has shown great efficacy in the treatment of IBD patients." (PMID 37185280, 2023). "Perinatal exposure to TiO2 also exacerbated the colitis, as evidenced by a reduced colon length associated with increased colonic mRNA expression and protein levels of IL-1β, IL-4, IL-12, IL-13, IFNγ and TNF-α." (PMID 37996842, 2023). "We show that mice with intestinal epithelial cell (IEC)-specific OTULIN deficiency exhibit increased susceptibility to experimental colitis and are highly sensitive to TNF toxicity, due to excessive apoptosis of OTULIN deficient IECs." (PMID 37598207, 2023). "The effects of anti TNF-α Ab, infliximab (10 mg/kg) were investigated in mouse models of colitis-associated cancer induced by intraperitoneally injected azoxymethane (AOM: 10 mg/kg)/orally administered dextran sodium sulfate (DSS: 2.5%) (AOM/DSS) in vivo." (PMID 37185713, 2023). "Then, we verified if anti TNF-α Ab inhibits carcinogenesis in mouse models of colitis-associated cancer in vivo." (PMID 37185713, 2023). "sakei K040706 isolated from soybean paste has been reported to inhibit pro-inflammatory factors such as nitric oxide (NO), TNF-α, IL-1β, and IL-6 and reduce inflammatory cell infiltration, thereby weakening the severity of colitis caused by DSS in mice." (PMID 36766113, 2023). "Concretely, PTSO was tested in two experimental models of colitis, which were associated with the regulation of cytokines in inflamed colonic tissue, leading to a reduction of pro-inflammatory cytokines IL-1β, TNF-α, and IL-6." (PMID 36986093, 2023). "Mucosal TNF levels are high in patients with anti-CTLA-4 therapy-induced colitis, with lower levels of TNF associated with response to steroids." (PMID 36776862, 2023). "For the clinical application of ADS024 in UC, it was shown that oral live ADS024 bacterial treatment successfully ameliorated DSS colitis in mice and with reduced weight loss, disease activity, mucosal injury, and colonic IL-6 and TNFα expression." (PMID 38268707, 2023).